MRFAP1L2 (Morf4 family associated protein 1 like 2)
Description:
May play a role in cell proliferation.
Synonyms: UPP
Tractability: No criterion of Open Targets' tractability assessment is met for any kind of drug.
Gene: Protein-coding gene on chromosome 4 (6,663,396 to 6,676,755, forward strand). Ensembl gene ENSG00000170846.
Gene Ontology:
Molecular function: protein binding
Biological process: regulation of cell cycle
Homologues: Orthologues: chimpanzee MRFAP1L2 (98% identical), macaque MRFAP1L2 (94% identical), pig MRFAP1L2 (58% identical), dog MRFAP1L2 (57% identical), mouse Mrfap1 (40% identical). Paralogues in human: MRFAP1L1 (45% identical), MRFAP1 (43% identical).